DVL1 (dishevelled segment polarity protein 1)
Diseases named in the same sentence as DVL1 in open-access papers (continued):
Sharing a sentence is not in itself a finding about the gene and the disease.
Robinow syndrome (13 papers, 2016 to 2025). Robinow syndrome (RS) is a rare genetic syndrome characterized by limb shortening and abnormalities of the head, face and external genitalia. "Mutations in DVL-1 can cause Robinow syndrome, which is characterized by bone abnormalities, highlighting its importance in bone function." (PMID 40299569, 2025). "Similar clinical signs are seen in Robinow syndrome in humans, a hereditary disorder caused by gene defects in the Wnt signaling pathway, including DVL1, DVL3, ROR2, WNT5A, FZD2 and NXN." (PMID 33599851, 2021). "Of these, receptor tyrosine kinase-like orphan receptor 2 (ROR2) and nucleoredoxin (NXN) are linked to autosomal recessive Robinow syndrome, whereas dishevelled genes (DVL1, DVL2 and DVL3), WNT5A and Frizzled2 (FZD2) have autosomal dominant inheritance (autosomal dominant Robinow syndrome)." (PMID 38967226, 2024). "In this study, we investigated human mutations in DVL1 that cause Robinow syndrome." (PMID 36916233, 2023). "The mutations of APC may cause Gardner syndrome, besides gene mutations of Ror2, Dvl1, Dvl3 and Wnt5a are associated with Robinow syndrome." (PMID 37194731, 2023). "Similarly, frameshift variants in DVL1, a recently reported disease gene for Robinow Syndrome (MIM#616331), also evaded detection or were interpreted as missense by the WES analysis pipeline." (PMID 27435318, 2016). "Misregulated DVL1 alters chondrogenic differentiation and promotes chondrocyte apoptosis, thus leading to cartilage damage in Robinow syndrome." (PMID 40299569, 2025). "Among the genetic causes associated with these phenotypes, pathogenic variants in DVL1/DVL3 and WNT5A (all (i.a.)for Robinow syndrome) and TCTN3 (orofaciodigital syndrome 4) have been identified." (PMID 34629465, 2022). "The location of the truncation of the protein is remarkably similar to the effect of mutations within the other Dishevelled family members, DVL1 and DVL3, that lead to Robinow syndrome in people." (PMID 30521570, 2018). "Mutations in genes from WNT pathways, including ROR2, FZD2, WNT5A, DVL1, and DVL3, have all been found to cause Robinow syndrome in humans." (PMID 30521570, 2018). "One case (101-PRE) carried a de novo frameshift variant in DVL1 previously reported in multiple patients with Robinow syndrome (DRS2, MIM: 616331)." (PMID 30266093, 2018). "As multiple genes are involved, the pathogenesis of Robinow syndrome could result from an imbalance of either branch of WNT signaling pathways, as we recently reported for DVL1 variants and others for reported variants in FZD2." (PMID 38967226, 2024). "Importantly, analogous frameshift mutations in the human DVL1 and DVL3 genes cause Robinow syndrome, a congenital disorder characterized by similar craniofacial, limb and vertebral malformations." (PMID 30521570, 2018). "In addition to the bulldog DVL2 frameshift mutation, human mutations causing Robinow syndrome have been identified in WNT5A, ROR2, FZD2, DVL1, and DVL3, which are all major components of the WNT5A-ROR pathway." (PMID 30521570, 2018). "Analogous truncations in the same regions of human DVL1 and DVL3 proteins result in Robinow syndrome in humans." (PMID 30521570, 2018). "Most of the genes implicated in the pathogenesis of Robinow syndrome function in the non-canonical c-Jun N-terminal kinase (JNK)/planar cell polarity (PCP) pathway except for FZD2, DVL1, DVL2 and DVL3, which also operate in the canonical/β-catenin-mediated WNT pathway." (PMID 38967226, 2024).
colorectal cancer (12 papers, 2013 to 2026). A primary or metastatic malignant neoplasm that affects the colon or rectum. "Altogether, these discoveries emphasize the crucial role of DVL1 in coordinating the cellular and spatial dynamics of colorectal cancer, molding microenvironmental interactions and influencing tumor behavior." (PMID 40276499, 2025). "Together, these findings highlight the importance of DVL1 as a key player in colorectal cancer, providing valuable insights for targeted therapy and prognostic assessment." (PMID 40276499, 2025). "Our study reveals that DVL1 is significantly overexpressed in colorectal cancer (COAD) tissues compared to adjacent normal tissues, as demonstrated by both immunohistochemical staining and RNA-seq analysis." (PMID 40276499, 2025). "The comprehensive analysis of DVL1 expression in colorectal cancer, combining single-cell sequencing and spatial transcriptomics, reveals critical insights into the gene’s role within the tumor microenvironment." (PMID 40276499, 2025). "According to previous results, the “P3” segment (-1422 ~ -1261) of the 2 kb downstream of DVL1 was the binding site of FUBP1 in colorectal cancer." (PMID 36932454, 2023). "It was previously shown that LMO2 interacts with the Wnt signaling effector DVL-1/2 and attenuates the Wnt pathway in breast and colorectal cancers." (PMID 35805116, 2022). "DVL1 was found overexpressed in multidrug-resistant colorectal cancer (CRC) cells." (PMID 42283820, 2026). "Meanwhile, FUBP1 was shown to promote DVL1 transcription in colorectal cancer." (PMID 36932454, 2023). "A previous study indicated that FUBP1 could promote DVL1 transcription to activate Wnt/β‐catenin pathway in colorectal cancer." (PMID 36932454, 2023). "CCK-8 proliferation assays demonstrated that DVL1 overexpression enhances cellular growth kinetics in both HCT116 and SW620 colorectal cancer models, whereas genetic silencing of DVL1 exerted potent growth-suppressive effects." (PMID 40276499, 2025). "Also, anti-LMO2 and anti-DVL1-1/2 immunofluorescence staining in breast and colorectal cancer cells revealed that LMO2 was predominantly located and co-localized with DVL-1/2 in the cytoplasm." (PMID 27779255, 2016).
lung carcinoma (11 papers, 2011 to 2024). "The highest-ranked genes in both cohorts of primary lung cancers and LC-BrMs included CCNL2, DVL1, ATAD3A, AGRN, and ISG15, where mutation patterns were clustered for the patients." (PMID 39593114, 2024). "In lung cancer, DVLs was reportedly to activate Wnt pathway and brain metastasis had increased expression of DVL1 and DVL3, which are potential targets of hsa_circ_0002360 and hsa_circ_0009117, respectively." (PMID 35123506, 2022). "DVL1 affects the biological behavior of lung carcinoma cells primarily through the β-catenin (canonical Wnt) pathway, while DVL3 acts primarily through the p38 and JNK pathways." (PMID 36035311, 2022). "DVL-1 nuclear staining was observed in almost 54% of cases with a significant increase in nuclear β-catenin staining in lung carcinomas." (PMID 34659647, 2021). "In the present study, 31 brain metastases that originated from primary lung carcinomas were analyzed regarding over expression of Dishevelled-1 (DVL1), Dishevelled-3 (DVL3), E-cadherin (CDH1) and beta-catenin (CTNNB1)." (PMID 24933634, 2014). "The authors report on downregulation of DVL1 RNA in glioblastoma and upregulation of DVL3 RNA in lung cancer." (PMID 30468298, 2019). "The work presented in this paper focused on the analysis of different expression levels of Dishevelled-1 (DVL1), Dishevelled-3 (DVL3), beta-catenin (CTNNB1) and E-cadherin (CDH1) in brain metastases that originated from primary lung carcinomas." (PMID 24933634, 2014). "Our investigations of DVL1 and DVL3 protein levels showed overexpression in brain metastasis of lung cancers." (PMID 25358879, 2014). "Our results on DVL1, DVL3, beta-catenin and E-cadherin bring novel insights on the Wnt signaling role in brain metastases that originated from primary lung carcinomas." (PMID 24933634, 2014). "Since Dvl-1 and β-catenin function as positive regulators of the canonical Wnt signaling pathway, it is plausible that NKD1 may increase the invasive ability of lung cancer cells through activating the canonical Wnt pathway." (PMID 21599923, 2011).
non-small cell lung carcinoma (7 papers, 2013 to 2024). A group of at least three distinct histological types of lung cancer, including non-small cell squamous cell carcinoma, adenocarcinoma, and large cell carcinoma. "Dvl1 that is downregulated in AD, is overexpressed in several cancers including cervical cancer, non-small cell lung cancer, mesothelioma, breast and prostate cancer." (PMID 36829686, 2023). "Coexpression of Dvl-1 and IQ-domain GTPase-activating protein 1 (IQGAP1) in the cytoplasm and nucleus is closely related to the poor prognosis of non-small-cell lung cancer." (PMID 36726071, 2023).
cardiac hypertrophy (5 papers, 2015 to 2023). "Studies have also shown that Dvl-1 knockdown can block the Wnt/β-catenin signaling pathway, and stress-induced cardiac hypertrophy is improved." (PMID 33468190, 2021). "By knockout Dvl-1 gene, ANF and BNP expression decreased, AKT activity was inhibited, but GSK-3β activity was activated, which relieved cardiac hypertrophy caused by overload pressure." (PMID 26282432, 2015). "Van de Schans and colleagues demonstrated that interruption of Wnt signaling in the mice lacking the Dvl-1 gene delays the onset of pressure overload-induced cardiac hypertrophy." (PMID 34603797, 2021).
cardiomyopathy (5 papers, 2014 to 2025). A disease of the heart muscle or myocardium proper. "However, emerging research indicates that cardiac overexpression of Dishevelled 1 (Dvl-1) is associated with the development of cardiomyopathy." (PMID 39482911, 2025). "Interestingly, evidence is accumulating that DVL1 is functionally associated with Wnt/Ca2+ and CamKII signaling in cardiomyopathy, in excitory synapses in the rat spinal chord and in convergent extension movements in Xenopus gastrulation, indicating a functional specification of DVL1." (PMID 28603713, 2017). "Although this study focuses on the interaction of post-tumor inflammation with the dysfunction of VSMC and the mechanism of DVL1 in sepsis-induced cardiomyopathy (SIC), the field of medical research is broad and interconnected." (PMID 40276499, 2025). "The loss of CaMKII had no impact on Dvl-1-induced activation of β-catenin or JNK, indicating that CaMKII was the major effector of Dvl-1 overexpression-induced cardiomyopathy." (PMID 35461308, 2022).
autosomal dominant Robinow syndrome (4 papers, 2018 to 2025). Autosomal dominant Robinow syndrome (DRS) is the more common type of Robinow syndrome (RS) characterized by mild to moderate limb shortening and abnormalities of the head, face and external genitalia. "All variants known to cause autosomal dominant Robinow syndrome occur in genes within the Wnt signaling pathway (DVL1, DVL3, or WNT5A)." (PMID 40796658, 2025). "The function of Dvl C-terminal region in Wnt signaling is further demonstrated in autosomal-dominant Robinow syndrome caused by de novo frameshift mutations in human DVL1 and DVL3 genes, which delete and replace the C-terminal region after the DEP domain." (PMID 33102490, 2020). "Indeed, our previous work on autosomal dominant Robinow syndrome DVL1 frameshift mutations (1519ΔT, 1529ΔG and 1615ΔA) and a WNT5A missense mutation (248G>C) found that the variants retained activity and were sufficient to reduce size and change bone shape." (PMID 38967226, 2024). "Previous studies from our laboratory have demonstrated that autosomal dominant Robinow syndrome WNT5A and DVL1 variants have dominant-negative effects on chondrogenesis, leading to abnormal bone morphology." (PMID 38967226, 2024). "Previously, our laboratory has investigated the effects of autosomal dominant Robinow syndrome WNT5A variants on jaw and limb development, and the effects of DVL1 variants on limb development." (PMID 38967226, 2024).
colon cancer (4 papers, 2015 to 2022). "In an analysis of a GEO dataset, expression levels of EpCAM, BCL9, and DVL1 were increased in colon cancer liver metastasis compared with primary tumors." (PMID 34790117, 2021). "Here, we validated that Wnt pathway genes such as DKK-1, DVL-1 and Wnt10A are indeed positively regulated by Fra-1 in both HT29 and HCT15 colon cancer cell lines." (PMID 26646695, 2015). "Importantly, most of WNT pathway genes induced by MYC, including DVL1, LEF1, RUVBL1, and RUVBL2, were also upregulated in tumor tissues when compared with the normal tissues from the same patients, suggesting that these genes may play a major role in colon cancer cells." (PMID 31623618, 2019).
craniorachischisis (4 papers, 2013 to 2018). Craniorachischisis is the most severe form of neural tube defect in which both the brain and spinal cord remain open to varying degrees. "The low penetrance of craniorachischisis in Dlgh-1−/− embryos on the C57BL/6J background is similar to observations of low penetrance of craniorachischisis in Dvl1−/−;Dvl2−/− mice on the C57BL/6J background." (PMID 23349879, 2013). "In one type of digenic example, mutants are homozygous at both of two homologous PCP genes with functional redundancy (e.g., Dvl1;Dvl2 or Fzd3;Fzd6) and nearly all embryos have craniorachischisis; homozygotes for any one of these genes do not." (PMID 30134561, 2018). "A severe NTD, craniorachischisis, is found in several mouse PCP-signaling mutants, including loop-tail (Lp) [Vangl2] mutants, crash [Celsr1] mutants, circletail [Scribble1], dishevelled 1 (Dvl1) and Dvl2 double mutants, and frizzled 3 (Fz3) and Fz6 double mutants." (PMID 23242429, 2013).
glioma (4 papers, 2017 to 2023). A benign or malignant brain and spinal cord tumor that arises from glial cells (astrocytes, oligodendrocytes, ependymal cells). "Combined collective public datasets from eight studies that are examining low‐grade gliomas and glioblastomas encompassing 4216 samples demonstrate the following distribution: somatic mutations were found in 8/4216 (0.19%) cases for DVL1, 12/4216 (0.28%) for DVL2 and 5/4216 (0.12%) for DVL3." (PMID 30468298, 2019). "Peng at al reported that in addition to being upregulated in high-grade gliomas, CTHRC1 expression correlated with genes associated with the Wnt Signaling pathway (DVL3, DVL1, DVL2, ROR2, WNT3A, FZD6 and FZD5)." (PMID 36190948, 2022). "Additionally, tumor treating fields (TTF) -mediated downregulation of circMMD can inhibit glioma progression by the FUBP1/FIR/DVL1 and miR-15b-5p/FZD6 pathways." (PMID 37723588, 2023).
prostate carcinoma (4 papers, 2014 to 2023). A carcinoma that arises from epithelial cells of the prostate gland. "In prostate cancer, DVL1/2/3 are rarely mutated (<1%), however DVL3 is amplified in up to 2.2% of primary cases, and as many as 8.8% of metastatic cases." (PMID 35204808, 2022). "Their sample of 20 primary prostate cancer showed significant over expression of DVL1 (65%) and correlation to beta-catenin’s expression." (PMID 24933634, 2014). "Interestingly, DVL1 amplification and over-expression were observed in breast and prostate cancers respectively, while DVL3 mRNA was significantly increased in pleural effusions from patients with lung cancer and was over-expressed in NSCLC." (PMID 35204808, 2022).
triple-negative breast carcinoma (4 papers, 2019 to 2021). An invasive breast carcinoma which is negative for expression of estrogen receptor (ER), progesterone receptor (PR), and human epidermal growth factor receptor 2 (HER2). "Using Kaplan Meier survival curves, we compared whether different expression levels of DVL-1 has any association with overall survival (OS) in triple-negative breast cancer patients." (PMID 34659647, 2021). "We had previously reported that DVL-1 protein expression was higher in triple-negative breast cancer cell (TNBC) line models." (PMID 34733415, 2021). "Interestingly, we also found that high expression of DVL-1 was associated with poor overall survival in basal or triple-negative breast cancer (TNBC), suggesting that the expression of DVL-1 could affect the prognosis of triple-negative breast cancer." (PMID 34659647, 2021). "Additionally, novel insights recently reported by our group demonstrate that a DVL-1 post-translational acetylation promotes nuclear localization in triple-negative breast cancer, highlighting a novel molecular switch that regulates subcellular localization of DVL proteins." (PMID 33126517, 2020). "Moreover, our results are the first to demonstrate that SIRT-1 and HDACs regulate DVL-1 acetylation levels and pharmacological inhibition of these lysine deacetylases results in altered acetylation levels of DVL-1 in two triple-negative breast cancer cell lines." (PMID 31700102, 2019). "We observed that DVL-1 protein levels were significantly higher in luminal B and HER2 amplified tumors, but the highest expression was in triple-negative breast cancers compared to non-cancer tissues." (PMID 34733415, 2021).
astrocytoma (3 papers, 2019 to 2021). "Our previous work on DVL1 in astrocytoma showed the high frequency of MSI in all grades of astrocytomas, while LOH was detected only in glioblastomas (in 8.6% of samples)." (PMID 34769425, 2021). "The plots demonstrated that for low‐grade astrocytomas, the low expression levels of DVL1 and DVL2 are correlated to better both overall and disease‐free survival." (PMID 30468298, 2019). "DVL1 might be involved in the early stages of astrocytoma malignancy." (PMID 34456184, 2021). "Key regulators of the Wnt signalling, DVL1, DVL2 and DVL3, in astrocytomas of different malignancy grades were investigated." (PMID 30468298, 2019).
breast tumors (3 papers, 2021 to 2023). "In breast tumors, mir-1247-5p promotes tumor growth via the Dishevelled1(DVL1)/Wnt/β-catenin signaling pathway, which promotes the differentiation of skeletal cells and accelerates bone regeneration." (PMID 35360081, 2022). "DVL1 has been shown to be overexpressed in primary breast tumors compared to non-cancerous breast tissues, and DVL1 protein has been found to be more present in the cytoplasm of cancer cells compared to that of normal epithelial cells in breast tumors." (PMID 36936429, 2023).
glioblastoma (3 papers, 2019 to 2023). The most malignant astrocytic tumor (WHO grade IV). "Glioblastomas displayed predominant low DVL1 expression, while anaplastic, pilocytic and diffuse astrocytomas showed predominantly moderate and strong signals." (PMID 30468298, 2019). "Microsatellite instability at DVL1 locus was detected in 28.6% of pilocytic, 61.5% diffuse, 45.5% anaplastic astrocytomas and 34.3% of glioblastomas." (PMID 30468298, 2019). "Accordingly, glioblastomas had a lower number of cells with strong DVL1 expression as compared with pilocytic (P = 0.001) and anaplastic astrocytomas (P = 0.001)." (PMID 30468298, 2019). "Furthermore, deletions of DVL1 were found in seven glioblastomas and deletions of DVL2 in two glioblastomas, while deletions of DVL3 were not reported." (PMID 30468298, 2019). "The highest number of samples with moderate and strong signal was present in the anaplastic astrocytoma group (92.9%) followed by pilocytic (85.7%) and diffuse (70%), while glioblastomas showed low or lack of DVL1 expression in 67.6% of cases." (PMID 30468298, 2019). "Collective results for both markers for DVL1 showed that MSI was detected in 28.6% of pilocytic, 61.5% diffuse, 45.5% anaplastic astrocytomas and in 34.3% of glioblastomas, while LOHs were found in 18.2% of anaplastic and 17.2% of glioblastomas." (PMID 30468298, 2019).
lung adenocarcinoma (3 papers, 2021 to 2023). A carcinoma that arises from the lung and is characterized by the presence of malignant glandular epithelial cells. "Dvl1 positivity was considerably higher in lung adenocarcinomas than in lung squamous cell carcinomas and significantly higher in stages II-III than in stage I (P < 0.05)." (PMID 36741266, 2023).
acute myocardial infarction (2 papers, 2019 to 2025). Necrosis of the myocardium, as a result of interruption of the blood supply to the area. "For example, a mouse model of myocardial infarction showed the dysregulation of expression of WNT2, -4, -7b, -10b and -11 as well as FZD1, -2, -5, -8 and -10, and mice mutants for Dvl1 are more susceptible to infarct rupture after induction of myocardial infarction." (PMID 31382613, 2019).